OSER1 (oxidative stress responsive serine rich 1)
Synonyms: C20orf111; HSPC207; dJ1183I21.1; Perit1; Osr1
Tractability: PROTAC: ubiquitination databases record sites on it.
Gene: Protein-coding gene on chromosome 20 (44,195,939 to 44,210,872, reverse strand). Ensembl gene ENSG00000132823.
Subcellular location (Human Protein Atlas): Nuclear speckles; Nucleoli; Nucleoli rim
Gene Ontology:
Molecular function: protein binding
Biological process: cellular response to hydrogen peroxide
Cellular component: nucleus
Genetic constraint (gnomAD): Loss-of-function variants: 10 observed, 18.11 expected, observed/expected ratio (o/e) 0.55, 90% interval 0.34 to 0.94. The upper end of that interval is the gene's LOEUF score, 0.94, which puts it in group 3 of 6, group 1 being the genes least tolerant of losing a copy. Missense variants: 246 observed, 283 expected, observed/expected ratio (o/e) 0.87, 90% interval 0.78 to 0.97. Synonymous variants: 94 observed, 105.28 expected, observed/expected ratio (o/e) 0.89, 90% interval 0.75 to 1.06.
Homologues: Orthologues: chimpanzee OSER1 (99% identical), macaque OSER1 (98% identical), dog OSER1 (93% identical), pig OSER1 (91% identical), rabbit OSER1 (91% identical), guinea pig OSER1 (89% identical), mouse Oser1 (87% identical), rat Oser1 (86% identical), tropical clawed frog oser1 (57% identical), zebrafish oser1 (43% identical), Drosophila melanogaster CG5056 (22% identical), Caenorhabditis elegans F02E9.5 (12% identical).
Diseases named in the same sentence as OSER1 in open-access papers:
OSER1 is named in the same sentence as 4 diseases in open-access papers, as found by Europe PMC text mining. Sharing a sentence is not in itself a finding about the gene and the disease. The quoted sentences say what the papers report.
non-small cell lung carcinoma (1 paper, 2021). A group of at least three distinct histological types of lung cancer, including non-small cell squamous cell carcinoma, adenocarcinoma, and large cell carcinoma. "The lncRNA OSER1-AS1promotes the deterioration of non-small cell lung cancer by sponging microRNA‐433‐3p to further increase Smad2 expression." (PMID 34101736, 2021).
primary immunodeficiency (1 paper, 2024). "Among pathways related to OSER1, the first 14 (beta alanine metabolism, nitrogen metabolism, etc.)were enriched in the high expression group, and the remaining six (glyoxylate and dicarboxylate metabolism, primary immunodeficiency, etc.)were enriched in the low expression group." (PMID 39022342, 2024).
rheumatoid arthritis (1 paper, 2024). A chronic, systemic autoimmune disorder characterized by inflammation in the synovial membranes and articular surfaces. "The long noncoding RNA OSER1 plays a crucial role in the inflammation and apoptosis of rheumatoid arthritis fibroblasts, and its low expression was markedly associated with poor survival of cancer patients." (PMID 39022342, 2024).
OSER1 also shares sentences with these, for which no sentence is quoted: cancer (2 papers).